GLI1 (GLI family zinc finger 1)
Diseases named in the same sentence as GLI1 in open-access papers (continued):
Sharing a sentence is not in itself a finding about the gene and the disease.
medulloblastoma (continued). "On the other hand, another report indicates that only phosphorylation at Ser408 on GLI1 by AMPK is crucial for GLI1 degradation and for the reduction of HH-driven cell growth in human medulloblastoma." (PMID 30934935, 2019). "Mocetinostat (MGCD0103), an HDAC1/HDAC2 inhibitor, is found to target Gli1 acetylation to truncate SHH signaling in medulloblastoma cells." (PMID 31788346, 2019). "In summary, these findings highlight a key role for PI3K/mTOR signalling in GLI1 regulation in HH-driven cancers and suggest that combined PI3Kα/mTOR inhibition may be particularly interesting for the development of effective treatment strategies in high-risk medulloblastomas." (PMID 31492956, 2019). "We demonstrate that this multitarget agent suppresses medulloblastoma growth in vitro and in vivo through antagonism of Smo and Gli1, which is a novel mechanism of action in Hh inhibition." (PMID 31601026, 2019). "KCASH2 has been previously shown to suppress medulloblastoma cell line DAOY growth by negatively regulating Hh/Gli1 signaling." (PMID 31685809, 2019). "In medulloblastoma cells MEKK2/3 mediates the negative modulation of FGF on HH pathway, by interacting with GLI1 and suppressing HH-dependent medulloblastoma cell growth." (PMID 31244888, 2019). "In a mouse medulloblastoma model, with a constitutive activation of Hh signaling pathway, itraconazole effectively downregulated GLI1 expression." (PMID 31035664, 2019). "In a medulloblastoma allograft model, saridegib demonstrated dose-dependent inhibition of Hh pathway via downregulation of GLI1 mRNA expression, which correlated with prolonged survival." (PMID 31035664, 2019). "In support of this, selective inhibition of HDAC1/2 results effective in inhibiting HH signaling and reducing tumor growth in Shh-dependent medulloblastoma mouse models through increased acetylation of Gli1 at Lys518." (PMID 31244888, 2019). "Further investigation of the species-specific effect of AMPK on GLI1 and medulloblastoma is warranted." (PMID 30360486, 2018). "In this study, however, we disclosed an inhibitory role of MEKK2/3 on GLI1 activity, which can suppress the cell growth of Daoy, a Hh pathway-dependent medulloblastoma cell line." (PMID 29662197, 2018). "To examine GLI1 function, we generated three GLI1-stable expression cell lines in a human medulloblastoma cell line (DAOY) and two mouse cell lines (NIH3T3 and mouse embryonic fibroblast cells, MEF)." (PMID 28562331, 2017). "We found that depletion of Gli1/2 from Shh-stimulated CGNPs or SmoM2-driven medulloblastoma cells (Smo MO) in zebrafish embryos down-regulated the expression of Kapβ2, suggesting that Kapβ2 is a Shh-responsive gene." (PMID 28777795, 2017). "SmoM2-induced medulloblastoma cells were cultured in vitro for a short period of time and infected with lentiviruses expressing shRNAs for Kapβ2 or Gli1/2." (PMID 28777795, 2017). "Although hedgehog network activation induces basal cell carcinoma and medulloblastoma, data connecting hedgehog signaling and breast tumorigenesis are largely correlative, although Gli1 overexpression in mice induces tumorigenesis." (PMID 28275010, 2017). "BCOR suppresses the tumor progression of SHH medulloblastoma by a BCL6/BCOR/SIRT1 complex that induces epigenetic repression of GLI1 and GLI2." (PMID 27825128, 2016). "Harmine treatment of murine BCC cells reduced Gli1 expression in a concentration-dependent manner, and like in human medulloblastoma cells, RNAi mediated perturbation of Dyrk1b efficiently inhibited Gli1 protein expression, while depletion of Dyrk1a did not." (PMID 26784250, 2016).
medulloblastoma (continued). "Strikingly, Fbxl17 mRNA was found to be significantly increased in the SHH‐subtype medulloblastoma and the levels of Fbxl17 and Gli1 positively correlated (Spearman's rho = 0.5640; P < 0.00001)." (PMID 27234298, 2016). "The positive feedback loop formed by Gli1 and Hck amplifies Shh signaling output and contributes to medulloblastoma cell growth." (PMID 26619401, 2015). "In medulloblastoma in which Gli1 is highly expressed and activated, we observed Tyr phosphorylation of endogenous Gli1." (PMID 26619401, 2015). "In their study, microarray analyses disclosed that when medulloblastoma DAOY cells treated with 20 μM curcumin showed 2.4-fold downregulation of Gli1 expression, which is a key effector in Hh signaling." (PMID 26619402, 2015). "Disrupting Gli1–Hck feedback loop would be a promising treatment strategy for Shh-type medulloblastoma." (PMID 26619401, 2015). "Our data indicate that high level of Hck is required for maximum Gli1 activities and oncogenic functions in medulloblastoma." (PMID 26619401, 2015). "As Hck is a novel enhancer for Gli1 oncogenic activities in medulloblastoma, Hck is a potential treatment target." (PMID 26619401, 2015). "Taken together, our results indicate that increased Hck expression in medulloblastoma induced by abnormally active Shh signaling enhances Gli1 oncogenic activities and contributes to tumor growth." (PMID 26619401, 2015). "It has previously been shown that activation of Shh or overexpression of Gli1 induced Bmi1 expression and knockdown of Bmi1 reduced medulloblastoma growth." (PMID 26286140, 2015). "In summary, a novel positive feedback loop contributes to maximal Gli1 oncogenic activities in Shh-induced tumors such as medulloblastoma." (PMID 26619401, 2015). "In Shh-induced medulloblastoma, both Gli1 and Hck are expressed at high levels and Gli1 is Tyr phosphorylated." (PMID 26619401, 2015). "One of the target genes of Gli1 is the polycomb protein Bmi1, a transcriptional suppressor that is upregulated upon Shh activation in medulloblastoma." (PMID 26286140, 2015). "High levels of Sufu were also found in developing cerebellum and in medulloblastoma, indicating inhibition of Shh/Gli1 activities despite activation of Shh signaling." (PMID 26619401, 2015). "GANT61 treatment reduced 40% of the PAX6 expression in canine OSA cells which is in agreement with a previous study wherein GLI1 knockdown reduced the expression of PAX6 in human medulloblastoma." (PMID 24810746, 2014). "While in HaCaT cells induction of SOCS1 by GLI1 is moderate compared to GLI2act, strong expression of SOCS1 was found in the medulloblastoma cell line DAOY in response to either GLI1 or GLI2act expression." (PMID 24058673, 2013). "Gli1 is necessary and sufficient for disease progression in basal cell carcinoma and medulloblastoma." (PMID 23900341, 2013). "Overactivated HH signaling and Gli1 overexpression play a central role in medulloblastoma tumorigenesis." (PMID 20433698, 2010). "To complete this study, we determined the expression of Cyclin D2 in 6 medulloblastoma cell lines and 14 tumor samples, and overall, we observed high expression levels of Cyclin D2 that correlated with high levels of GLI1 expression." (PMID 21059263, 2010). "Similar upregulation patterns of the Gli1 transcripts were also observed in medulloblastomas from Ptch1+/- mice maintained on a C57BL/6 genetic background." (PMID 20433698, 2010). "We attempted to determine Plakoglobin expression in the Daoy medulloblastoma cell line upon GLI1 silencing." (PMID 21059263, 2010). "Silencing expression of GLI1 resulted up-regulation of all target genes in the medulloblastoma cell line, while only PTCH1 was up-regulated in astrocytoma." (PMID 21059263, 2010).
medulloblastoma (continued). "Future work will focus on identifying the precise binding sites of these derivatives on Gli1 and evaluating their effects on key mechanisms of tumor cell proliferation, particularly in cancers with aberrant HH signaling, such as medulloblastoma or rhabdomyosarcoma." (PMID 40651614, 2025). "Thus, p38α-mediated phosphorylation on Ser937 of GLI1 was involved in the tumorigenesis of medulloblastoma and the sensitivity to chemotherapy of SMO antagonists." (PMID 38307877, 2024). "In addition, high-resolution mass spectrometry (MS) analysis for GLI1 purified from Daoy cells, human medulloblastoma cells, revealed six endogenous potential phosphorylation sites, including Ser70, Ser569, Ser927, Ser937, Thr601 and Thr1074." (PMID 38307877, 2024). "Also, abnormal expression of proteins downstream of this pathway (e.g., Smo, Gli1, Gli2, etc.)is importantly associated with the development of SHH-type medulloblastoma." (PMID 37821528, 2023). "Indeed, it was shown that Gli1/2 nuclear translocation in response to Shh requires Rac1 activation, and Rac1 is involved in the progression of Shh-type medulloblastoma." (PMID 36681682, 2023). "Moreover, activation of AIP4 interacts with and induces Gli1 degradation, while mutation of AIP4-dependent degron in Gli1 enhances medulloblastoma growth, migration, invasion, and in vitro transforming activity, suggesting AIP4 functions as a tumor suppressor." (PMID 35177982, 2021). "The overexpression of this protein sustains clonogenic growth, migration and tumorigenicity of medulloblastoma cells, and recently it was demonstrated to interact with GLI1 and GLI2 proteins stimulating the trans-activation of the Sonic Hedgehog pathway in medulloblastoma." (PMID 34445164, 2021). "Similarly, ARRB1 overexpression in SHH-medulloblastoma CSCs resulted in decreased Gli1 protein levels." (PMID 33297302, 2020). "However, another report indicates that only phosphorylation at Ser408 is critical for GLI1 degradation and appears to reduce HH-driven cell growth in human medulloblastoma." (PMID 31244888, 2019). "Patients with SHH-driven medulloblastoma frequently exhibit either germline or somatic mutations and copy-number alterations in genes that regulate the Hedgehog (HH) signalling pathway such as PTCH1, SUFU, SMO, GLI1, GLI2 and MYCN8." (PMID 31492956, 2019). "Given the widespread association of GLI1 with many human cancers including glioblastoma, basal cell carcinoma, lung cancer, GI cancers, prostate cancer, medulloblastoma and rhabdomyosarcoma, it is important to understand key elements of the regulation of GLI1 expression." (PMID 31085420, 2019). "The finding of a FOXS1/GLI1 feedback loop may also provide additional possibilities to develop effective markers for SHH medulloblastoma." (PMID 30098229, 2018). "These substrates may include other drivers of SHH-medulloblastoma tumorigenesis, in addition to GLI1." (PMID 30314361, 2018). "Moreover, FOXS1 is both highly expressed and positively correlated with GLI1 in medulloblastoma samples of the Sonic HH subgroup, further arguing for the existence of FOXS1/GLI1 interplay in human tumors." (PMID 30098229, 2018). "Moreover, expression of MEKK3 in another medulloblastoma cell line D341 Med inhibited cell proliferation, expression of Hh pathway target genes, and reduced GLI1 protein levels." (PMID 29662197, 2018). "An interesting question in this context is whether the FOXS1 co‐expression to the GLI1 oncogene in medulloblastoma and prostate cancer promotes or inhibits tumorigenesis." (PMID 30098229, 2018). "Moreover, stabilized β-catenin interacts with GLI1 in murine medulloblastoma spheres, which was increased under lithium treatment mediating GLI1 degradation associated with a G2/M cell cycle arrest and induction of a senescent-like state." (PMID 28575066, 2017).
medulloblastoma (continued). "Similar to Gli1/2 RNAi, Kapβ2 knockdown in SmoM2-induced medulloblastoma cells diminished the expression of Shh target genes, including Gli1, Ptch1, CycD1, and N-Myc, leading to growth inhibition of the medulloblastoma cells as indicated by a cell survival assay." (PMID 28777795, 2017). "For example, Hh signaling may activate STAT3 activity in transcription-dependent manner via interactions between STAT3 and GLI1 as reported in both the medulloblastoma and granule neuron precursor cells." (PMID 27275540, 2017). "A medulloblastoma sample of the SHH subtype also expressed high level of GLI1." (PMID 27825128, 2016). "Finally, recent work demonstrates that activation of Ampk reduces Gli1 protein stability and transcription activity in medulloblastoma, therefore compromising Hh canonical responses." (PMID 27010359, 2016). "Collectively, this data unveil a novel mechanism of inhibition of Gli1 function, which is exclusive for human cells and may be exploited for the treatment of Medulloblastoma or other Gli1 driven tumors." (PMID 26843621, 2016). "Additionally, in Set A there are at least two genes whose expression is modified, Gli1 and Pdgfd, which are markers of Shh-type medulloblastoma." (PMID 27965576, 2016). "In medulloblastoma samples, Gli-1 expression was clearly correlated with Bcl-2 mRNA levels." (PMID 26716648, 2016). "Inhibiting Hck activities or disrupting the Hck–Gli1 feedback loop may be effective approaches for the treatment of Shh-type medulloblastoma and possibly other cancers with elevated Shh/Gli1 activities." (PMID 26619401, 2015). "Gli1 is one of the key oncogenic factors in Shh-induced tumors such as medulloblastoma." (PMID 26619401, 2015). "Indeed, we found that endogenous Gli1 is Tyr phosphorylated in medulloblastoma as indicated by 4G10 antibody immunoprecipitation." (PMID 26619401, 2015). "Downregulation of the β1-subunit could be mimicked by expressing the transcription factors Gli1, a well-known member of the Shh signaling cascade, and Bmi1, a polycomb protein that can be induced by Shh/Gli1 in medulloblastoma." (PMID 26286140, 2015). "In Shh-induced medulloblastoma, Hck is highly expressed and Gli1 is tyrosine phosphorylated, which may enhance the tumorigenic effects of the Gli1 oncogene." (PMID 26619401, 2015). "Thus, Gli1–Hck positive feedback loop enhances Gli1 oncogenic effects and contribute to the growth of medulloblastoma." (PMID 26619401, 2015). "We speculate that Hck is induced by high levels of Gli1 and that the positive feedback loop with Gli1 operates only in the presence of highly active Shh signaling such as that observed in medulloblastoma." (PMID 26619401, 2015). "This had the effect of stabilizing Gli1 and promoting medulloblastoma growth." (PMID 25369329, 2014). "Notably, KCTD11 downregulation is associated with Gli1 and Patch1 overexpression, demonstrating that KCTD11 tumor suppressor gene acts as an inhibitor of Hedgehog signaling not only in medulloblastoma but also in prostate cancer." (PMID 25045667, 2014). "Interestingly and in line with these observations, Hedgehog signaling-dependent mouse models for medulloblastoma development are apparently influenced by the Gli1 genotype." (PMID 20433698, 2010). "Silencing of GLI1 in Daoy cells indicated that GLI1 may up-regulate the expression of the homeodomain transcription factor I PAX6 in medulloblastomas." (PMID 21059263, 2010). "Additionally, we detected an inverse correlation in levels of expression of GLI1 and Plakoglobin in primary medulloblastoma samples, with the exception of two tumors." (PMID 21059263, 2010).
medulloblastoma (continued). "To determine whether GLI1 regulates Cyclin D2 in medulloblastomas, we quantified levels of Cyclin D2 transcript upon silencing of GLI1 by siRNA in the Daoy medulloblastoma cell line." (PMID 21059263, 2010). "Whether activated through canonical or non-canonical mechanisms, GLI1 aberrant activity is associated with Hedgehog-dependent cancers, including medulloblastoma, as well as other tumoral contexts." (PMID 39695131, 2024). "Thus, we hypothesized that Shh/Gli1 signaling pathway was involved in the anti-medulloblastoma mechanism of BDDD-721." (PMID 35802536, 2022). "Finally, FOXS1 expression highly correlated with GLI1 expression in SHH medulloblastoma." (PMID 30098229, 2018). "However, GLI1‐701G is less effective in promoting cell growth in medulloblastoma cells." (PMID 30098229, 2018). "Importantly and in line with our DYRK1B RNAi data, DYRKi treatment of SAG-treated SUFU-positive (WT MB +SAG) and untreated SUFU-depleted (ΔSufu MB) human medulloblastoma cells prevented GLI1 mRNA expression at comparable IC50 concentrations of 1.16 μM and 1.04 μM, respectively." (PMID 26784250, 2016). "It is important to highlight here again that in addition to GLI1 role in regulation of various mechanisms in tumor development, GLI1-induced disruption of ATR-CHK1 checkpoint signaling in the developing brain may generate the precursor lesions that lead to medulloblastoma formation." (PMID 26633513, 2015). "As Hck may also enhance Gli1 activities with kinase-independent activities, specific inhibitors disrupting the Hck–Gli1 feedback loop would be more effective in inhibiting Shh-type medulloblastoma cancer progression than general kinase inhibitors." (PMID 26619401, 2015). "Therefore, our results may support high expression and up-regulation of Plakoglobin by GLI1 in medulloblastomas." (PMID 21059263, 2010). "In this study, we demonstrate the synchronous expression of GPC6 with GLI family zinc finger 1 (GLI1) in both the developing cerebellum and medulloblastoma." (PMID 41320180, 2026). "Here, the authors find that SHH-inactivation of p38 results in stabilization of the transcription factor GLI1 via dephosphorylation at Ser937, resulting in expression of SHH genes and presenting a potential therapy strategy for medulloblastoma and BCC." (PMID 38307877, 2024). "In medulloblastoma cell lines, AMPK activation inhibits the transcriptional activity induced by the canonical SHH pathway through GLI1 phosphorylation." (PMID 38539429, 2024). "In mouse medulloblastoma spheroids (MB55 and MB5644), only vismodegib was found to significantly reduce GLI1 levels." (PMID 37393376, 2023). "Five genes were identified, including GLI1, which was reported to be regulated by the UHRF1/DNMT1 complex in medulloblastoma." (PMID 37380646, 2023). "The mPEG5kDa-cholane/GlaB micellar system can be properly exploited in the treatment of patients with medulloblastoma, particularly for those tumors showing resistance to SMO inhibitors or harboring GLI1 hyperactivation by SMO-independent mechanisms." (PMID 35163655, 2022). "In medulloblastoma allograft models, LEQ506 mediated near complete and sustained GLI1 mRNA inhibition." (PMID 35954384, 2022). "To translate the finding that GSK-J4 is a candidate to treat medulloblastoma, we measured Gli1 mRNA level changes before and after GSK-J4 treatments in a human Shh-type medulloblastoma cell line DaoY." (PMID 36531063, 2022). "In both medulloblastoma and glioma cells, PAX6 expression is controlled by SHH-GLI signaling events: GLI1 activates PAX6 expression in medulloblastomas but suppresses it in gliomas." (PMID 34012965, 2021). "On the contrary, preclinical study in medulloblastoma showed antagonistic role between FGFR1 and GLI1 expression, suggesting tissue-specific role of these pathways." (PMID 34722544, 2021).